REN (renin)
Diseases named in the same sentence as REN in open-access papers (continued):
Sharing a sentence is not in itself a finding about the gene and the disease.
Insulin resistance (continued). "Moreover, one factor that promotes insulin resistance is chronic stress caused by long-term exposure to stress hormones and pathways, prominent among which are the renin-angiotensin-aldosterone pathways." (PMID 39561140, 2024). "Previous studies have suggested that RAS-acting agents may reduce the risk of cognitive decline by favourably modulating the renin-angiotensin system, which involves mitigating inflammation, vascular dysfunction, and insulin resistance." (PMID 38281243, 2024). "Urea, oxidative stress, activation of the renin–angiotensin–aldosterone system, inflammation, and metabolic acidosis after renal injury may be the underlying mechanisms leading to insulin resistance." (PMID 39058804, 2024). "Stress and insulin resistance are likely linked through molecular pathways, including pancreatic beta cells, lipid metabolism, the renin-angiotensin system, the autonomic nervous system, the immune response system and endocrine hormones which are under the influence of stress." (PMID 37998065, 2023). "Furthermore, insulin resistance has also been associated with hyperactivated sympathetic tone, activation of the renin-angiotensin aldosterone system, and increased salt-sensitivity; all of which are implicated in hypertension." (PMID 37822556, 2023). "Additionally, in the state of insulin resistance, the body can activate the renin-angiotensin-aldosterone system, causing a decrease in renal blood flow, resulting in a decrease in UA excretion and an increase in the sUA." (PMID 35932038, 2022). "On the other hand, weight loss can lead to a meaningfully reduced renin-angiotensin-aldosterone system in plasma and adipose tissue, as well as a reduction in insulin resistance, which may contribute to the reduced blood pressure." (PMID 35390081, 2022). "Moreover, insulin resistance is associated with activation of renin–angiotensin–aldosterone system (RAAS) thus promoting the stimulating effects of angiotensin II on cellular growth and collagen production, which leads to myocardial hypertrophy and fibrosis." (PMID 33676510, 2021). "Low atrial natriuretic peptide (ANP) levels were associated with the activation of the renin-angiotensin system, which in turn could promote the development of insulin resistance and thus T2D." (PMID 33066780, 2020). "Studies undertaken to explore the mechanisms of T2DM and changes in the renin–angiotensin system that might lead to carcinogenesis found probable associations with hyperglycemia, inflammation, insulin resistance, and hormonal dysregulation." (PMID 32878139, 2020). "Most important, the prevalence of risk factors for atherosclerosis, for example, insulin resistance and dyslipidemia, is significantly higher in obese individuals, which is likely to reduce the relative impact of renin and aldosterone on atherosclerosis development." (PMID 32529242, 2020). "A previous study has proposed that uric acid-mediated upregulation of the adipose renin–angiotensin system may cause insulin resistance." (PMID 30271378, 2018). "In addition, vitamin D deficiency was accompanied with activation of the renin-angiotensin-aldosterone system, and the associated increase of parathyroid hormone has been related to insulin resistance." (PMID 25807387, 2015). "Moreover, weight loss leads to a decrease in plasma renin activity and aldosterone levels, resulting in a reduction in extracellular volume, a decline in sympathetic nervous system activity, and an improvement in insulin resistance." (PMID 40034990, 2025). "The activation of the renin-angiotensin system and insulin resistance is associated with subclinical vascular injury and early kidney damage, which may increase the risk of hyperuricemia if the glomerular hyperfiltration cannot fully compensate for the reduced urate excretion." (PMID 36432539, 2022).
Insulin resistance (continued). "However, the underlying mechanisms include an increasing body mass, insulin resistance, inflammation, renal endothelial dysfunction, oxidative stress, and altered renal haemodynamics, activation of the renin-angiotensin-aldosterone system and sympathetic nervous system, and dietary factors." (PMID 23690758, 2013). "Insulin resistance can reduce the production of NO and also over activate the sympathetic nervous system and the renin-angiotensin system, all of which contribute to vasoconstriction and elevated blood pressure." (PMID 40664455, 2025). "It is evident that CKM syndrome is complex syndrome characterized by a network of interconnected mechanisms, including but not limited to inflammation, oxidative stress, insulin resistance, and renin–angiotensin–aldosterone system dysregulation." (PMID 41516982, 2025). "Insulin resistance activates the sympathetic nervous system and the renin-angiotensin-aldosterone system, contributing to elevated blood pressure." (PMID 41037676, 2025). "Since ACE2/Ang 1-7 is the protective arm of the renin–angiotensin system, it initially works to offset increasing glucose levels and insulin resistance." (PMID 40564980, 2025). "In type 2 diabetes (T2D), renin levels are often elevated, promoting insulin resistance and metabolic dysfunction." (PMID 40564980, 2025). "Conversely, as kidney function declines, retention of uraemic toxins, oxidative stress, and renin–angiotensin–aldosterone activation aggravate insulin resistance, dyslipidemia, and systemic inflammation, worsening hepatic steatosis and promoting fibrogenesis." (PMID 41465744, 2025). "Potential underlying mechanisms involve activation of the sympathetic nervous system, insulin resistance, and the renin–angiotensin–aldosterone system." (PMID 40748558, 2025). "This relationship is presumably mediated by various adverse effects, including inflammation, insulin resistance, activation of the renin–angiotensin–aldosterone system, and stimulation of the sympathetic nervous system." (PMID 40725808, 2025). "The renin–angiotensin–aldosterone system (RAAS) significantly influences insulin resistance (IR) and its complications, particularly in hyperglycemic conditions." (PMID 39125938, 2024). "Insulin resistance can lead to the activation of the renin–angiotensin system, which is key driver of renal damage." (PMID 39713133, 2024). "Again, insulin resistance can increase BP through the renin–angiotensin–aldosterone system activation as well as acting through the central nervous system." (PMID 38337357, 2024). "A subset analysis of BMI-matched plus insulin resistance (IR)-matched women revealed only upregulation of tissue factor (TF) and renin in PCOS, potentially serving as biomarkers for cardiovascular risk in overweight/obese women with PCOS." (PMID 39858399, 2024). "Low levels of 1,25(OH)2D levels in the body can lead to deterioration of the RAS system by inducing abnormal metabolic profiles such as increasing renin, proteinuria, blood pressure, insulin resistance, and renal injury." (PMID 36873872, 2023). "Experimental studies have shown that high blood pressure upregulates pathways related to insulin resistance, while T2D triggers the overactivation of the renin-angiotensin-aldosterone system and sympathetic tone, resulting in elevated blood pressure." (PMID 37822556, 2023). "In obese individuals, adipocyte dysfunction contributes to vascular and systemic insulin resistance, as well as malfunction of the sympathetic nervous system and the renin–angiotensin–aldosterone system." (PMID 37081416, 2023). "T1D can be associated with metabolic disorders and several impaired pathways, including insulin signaling, and development of insulin resistance through the renin-angiotensin system (RAS)." (PMID 38092813, 2023). "Insulin resistance can also increase sodium retention in the kidney and activate the renin-angiotensin system to impose additional stress or injury to the myocardium." (PMID 37291516, 2023).
Insulin resistance (continued). "Diabetic cardiomyopathy is the concept that the myocardium is impaired by hyperglycemia, insulin resistance, advanced glycation end product accumulation, lipo-toxicity, activated renin–angiotensin–aldosterone system, oxidative stress, and other mechanisms." (PMID 35956232, 2022). "In fact, inflammation, insulin resistance, oxidative stress, and an overactive renin-angiotensin system preserve each other while negatively affecting endothelial and cardiovascular function and health." (PMID 35324651, 2022). "Increases in the Nox family during insulin resistance has been largely attributed to the renin–angiotensin system stimulation in other diabetic models." (PMID 35624791, 2022). "Obese hypertensives are prone to have poor prognosis because of excessive inflammation, insulin resistance, and activation of the renin-angiotensin-aldosterone axis." (PMID 36712259, 2022). "Oxidative stress is promoted by lipid abnormalities, leading to insulin resistance and increased production of renin–angiotensin–aldosterone system components." (PMID 36094942, 2022). "The adipose tissue excessively secretes adipocytokines, and the cytokines result in insulin resistance and subsequent activation of the sympathetic nervous system and the renin-angiotensin system in obese individuals." (PMID 36010315, 2022). "The effect of insulin resistance on arterial stiffness includes an increase in sympathetic activity and the activation of the renin-angiotensin-aldosterone system." (PMID 35146005, 2021). "Hyperuricemia activates the renin-angiotensin system, decreases nitric oxide synthase activity, stimulates vascular smooth muscle cell proliferation, and promotes insulin resistance." (PMID 33754652, 2021). "In obese individuals, adipose tissue excessively secretes adipocytokines, resulting in insulin resistance and subsequent activation of the sympathetic nervous system and the renin-angiotensin system." (PMID 33637130, 2021). "Instead, transgenic rodents overexpressing human renin are obese due to increased food intake and exhibit hyperglycemia, hyperinsulinemia, hyperlipidemia, and insulin resistance." (PMID 34107965, 2021). "Through the up-regulate activity of the renin–angiotensin–aldosterone system, insulin resistance and chronic hyperglycemia promoted hypertrophy and fibrosis of the vascular wall, consequently leading to stiffening of the artery." (PMID 34627312, 2021). "The responsible mechanisms include insulin resistance and activation of renin–angiotensin system (RAS), sympathetic nervous system, and oxidative stress." (PMID 34267672, 2021). "The likely pathophysiological mechanisms are the increase in adipose tissue together with insulin resistance, which leads to activation of the renin-angiotensin-aldosterone axis." (PMID 34393633, 2021). "Activation of p38 MAPK leads to high levels of glucose, plasma free fatty acids (FFAs), inflammatory cytokines and overactivation of the cardiovascular renin-angiotensin system (RAS) in insulin resistance and T2DM." (PMID 34358068, 2021). "Renin as well as angiotensin II have both been reported to promote inflammation and insulin resistance." (PMID 32529242, 2020). "Insulin-resistance also determines the hyperactivation of other systems such as renin-angiotensin-aldosterone system (RAAS) and symphatetic nervous system, with consequent hemodynamic and no hemodynamic effects." (PMID 32033349, 2020). "The underlying mechanisms include vascular inflammation, activation of the renin–angiotensin–aldosterone system, insulin resistance, and neurohormonal dysfunction." (PMID 32403968, 2020). "Several suggested mechanisms include metabolic disturbances, insulin resistance, microvascular disease, renin-angiotensin system activation, and excessive oxidative stress." (PMID 29682576, 2018).
Insulin resistance (continued). "Several recent reviews, including ours, clearly implicate the renin-angiotensin system (RAS) in the development of insulin resistance, type 2 diabetes, and cardiovascular complications." (PMID 29971102, 2018). "Possible described mechanisms for the antihypertensive potential of probiotics include the improvement of lipid profiles, insulin resistance, modulation of renin, the bioconversion of bioactive isoflavones and reduction in body weight." (PMID 29228000, 2017). "High potassium was found to improve insulin resistance by decreasing plasma renin activity and angiotensin 2 levels." (PMID 29246005, 2017). "Production of ROS is associated with local inflammation, impaired nitric oxide (NO) generation, activation of the renin-angiotensin-aldosterone system, insulin resistance, and fat accumulation, and promotes tumour cell proliferation, migration, and survival." (PMID 28418841, 2017). "Several factors are believed to contribute to the pathogenesis of diabetic cardiomyopathy, including insulin resistance, enhanced renin-angiotensin system activation, hyperglycemia, and damage from ROS." (PMID 26989452, 2016). "It is well acknowledged that central fat is metabolically active and leads to the activation of a series of pathophysiologic processes including activation of the renin-angiotensin system and development of insulin resistance." (PMID 24980215, 2014). "Renin-angiotensin-aldosterone system activation and insulin resistance were also risks for the development of cancer in addition to worsening myocardial damage." (PMID 24847804, 2014). "The underlying mechanism of latent myocardial damage was reported to be involved in renin-angiotensin-aldosterone system activation, sympathetic nervous activation, and insulin resistance." (PMID 24847804, 2014). "The activation of the classical angiotensin (Ang)-converting enzyme (ACE)/Ang II/Ang II type 1 receptor (AT1R) axis of the renin-angiotensin system (RAS) has been associated with islet dysfunction and insulin resistance." (PMID 23942780, 2013). "It is possible that other factors, such as intracellular acidification and some neurohumoral regulators, including the renin-angiotensin-aldosterone system are directly involved in the activation of NHE under the presence of insulin resistance." (PMID 23289667, 2013). "We argue this because in renin knockout mice, the metabolic phenotype of increased insulin sensitivity and resistance to high-fat diet-induced glucose intolerance and insulin resistance was reversed by Ang II infusion." (PMID 23308073, 2012). "Renin-angiotensin system overactivation via chronic Ang II infusion leads to the development of systemic insulin resistance in rodents." (PMID 23308073, 2012). "Medical treatment that interferes with various steps in the renin-angiotensin system improves glucose tolerance and insulin resistance." (PMID 21906391, 2011). "The renin-angiotensin system (RAS) reportedly plays an important role in insulin resistance, and suppression of angiotensin-II (AT-II) ameliorates insulin resistance." (PMID 19416517, 2009). "Probiotics have exhibited antihypertensive potential via the improvement of lipid profiles, insulin resistance, modulation of renin and the bioconversion of bioactive isoflavones." (PMID 19865517, 2009). "Some scholars propose that hyperinsulinemia resulting from insulin resistance may enhance the activity of the renin-angiotensin-aldosterone system, thereby contributing to elevated blood pressure." (PMID 39746074, 2025). "Currently, it is generally believed that high salt intake may affect NAFLD by influencing insulin resistance, endogenous fructose metabolism, and the function of the renin-angiotensin-aldosterone system (RAAS)." (PMID 40696706, 2025).
Insulin resistance (continued). "NAFLD may influence myocardial ischemia directly or indirectly via mechanisms including insulin resistance, activation of the renin-angiotensin system and sympathetic nervous system, systemic inflammation, oxidative stress, and alterations in gut microbiota." (PMID 40547531, 2025). "Chronic hyperglycemia, insulin resistance, and metabolic disturbances drive myocardial damage through renin–angiotensin–aldosterone system (RAAS) activation, oxidative stress, mitochondrial dysfunction, advanced glycation end product (AGE) accumulation, and persistent inflammation." (PMID 41158128, 2025). "Insulin resistance may also directly affect cardiovascular and kidney function by activating the renin-angiotensin-aldosterone system (RAAS) and the sympathetic nervous system." (PMID 40635894, 2025). "Insulin resistance disrupts these processes, leading to significant cardiac metabolic disturbances, autonomic dysfunction, subcellular signaling abnormalities, and activation of the renin–angiotensin–aldosterone system." (PMID 39125938, 2024). "Gender exerts a critical influence on CKM syndrome, affecting the disease severity and onset through intricate interactions involving sex hormones and key physiological pathways such as the renin–angiotensin system, oxidative stress, inflammation, vascular disease and insulin resistance." (PMID 39124622, 2024). "In addition, hyperinsulinemia resulting from insulin resistance helps activate the renin–angiotensin–aldosterone system, thereby promoting renal sodium retention." (PMID 39616407, 2024). "Finally, dyslipidemia leads to increased blood pressure by inducing insulin resistance, which in turn activates the renin-angiotensin system." (PMID 39193442, 2024). "In addition, MetS is followed by peripheral insulin resistance, chronic microinflammation, activation of oxidative and prothrombotic mechanisms, and deregulation of the renin-angiotensin axis." (PMID 38817671, 2024). "Polarization of macrophages and lymphocytes toward a pro-inflammatory phenotype can contribute to the progression of insulin resistance, possibly through the renin–angiotensin–aldosterone system, sympathetic activation and incretin modulators (e.g., DPP-4) and immune responses." (PMID 38715129, 2024). "Along with the genetics and environmental factors, other contributors such as aberrant activation of the renin–angiotensin system (RAS) and imbalanced gut microbiota can cause host energy metabolism disorders, leading to insulin resistance (IR), dyslipidemia, and other hallmarks of MetS." (PMID 39086603, 2024). "The mechanisms causing elevated blood pressure in obese patients are multifaceted, including the stimulation of the renin–angiotensin–aldosterone system, the overactivation of the sympathetic nervous system, insulin resistance, and alterations in adipose-derived cytokines." (PMID 39202062, 2024). "Insulin resistance induces hyperinsulinemia and hyperglycemia in hypertensive subjects, activating oxidative stress and inflammation and upregulating the activity of the renin-angiotensin-aldosterone-system." (PMID 39217344, 2024). "In addition, exacerbated insulin resistance leads to increased activity of the sympathetic nervous system and the renin–angiotensin–aldosterone system." (PMID 37993858, 2023). "Several studies have identified important roles for miR-27 in lipid metabolism, inflammation, angiogenesis, adipogenesis, oxidative stress, the renin-angiotensin system, insulin resistance, and type 2 diabetes, which have important roles in the onset and outcome of atherosclerosis." (PMID 37628623, 2023). "The pathological mechanisms underlying this association include adipose tissue inflammation, dyslipidemia, insulin resistance, chronic systemic inflammation, oxidative stress, and overactivation of the sympathetic nervous system, as well as the renin-angiotensin aldosterone system." (PMID 37521339, 2023).